PKMYT1 (protein kinase, membrane associated tyrosine/threonine 1)
Diseases named in the same sentence as PKMYT1 in open-access papers (continued):
Sharing a sentence is not in itself a finding about the gene and the disease.
ovarian carcinoma (8 papers, 2017 to 2025). A malignant neoplasm originating from the surface ovarian epithelium. "We found that the combination of WEE1 and PKMYT1 inhibition exhibited synergistic effects in eradicating ovarian cancer cells and organoid models at a low dose." (PMID 37325550, 2023). "In ovarian cancer, SIRT3 enhances the ability of protein kinase membrane associated tyrosine/threonine 1 (PKMYT1) to promote cell migration and invasion, thus accelerating cancer metastasis." (PMID 35832551, 2022). "Notably PKMYT1 is overexpressed in CCNE-amplified ovarian carcinoma, and currently PKMYT1i RP-6306 is in clinical trials in this setting." (PMID 38279263, 2024). "Notably, PKMYT1 expression was reported to be upregulated in ovarian cancers and correlated with poor prognosis, making it an appealing therapeutic target." (PMID 37325550, 2023). "In addition to high proliferation rate, ovarian cancers almost ubiquitously overexpress PKMYT1, suggesting their dependence on PKMYT1 activity." (PMID 37325550, 2023). "The PKMYT1 inhibitor Lunresertib is already in clinical trial (NCT04855656) and shows promising therapeutic efficacy to ovarian cancer." (PMID 41286306, 2025). "We pre-treated select ovarian cancer cells (OVCAR3 and KURAMOCHI) and organoids (EOC884 and EOC989) with gemcitabine for 18 h followed by combined WEE1 and PKMYT1 inhibition." (PMID 37325550, 2023). "Blocking PKMYT1 activity was effective in eradication of CCNE1-amplified ovarian cancer cells, but not cell lines without amplification through preventing completion of DNA synthesis and increasing the rates of premature mitotic entry." (PMID 38279263, 2024). "Interestingly, by analyzing The Cancer Genome Atlas (TCGA) ovarian carcinoma (OV) database, we noticed that, similar to the strong correlation between the levels of WEE1 and PKMYT1 and that of their substrate CDK1, the level of ODF2L also significantly correlated with that of CDK1." (PMID 36378528, 2023).
colorectal cancer (7 papers, 2020 to 2021). A primary or metastatic malignant neoplasm that affects the colon or rectum. "PKMYT1 is highly expressed in multiple cancer cells, including gastric, lung and colorectal cancer, which correlates with poor prognosis and disease progression." (PMID 34366863, 2021).
glioblastoma (7 papers, 2021 to 2025). The most malignant astrocytic tumor (WHO grade IV). "Other studies showed that the loss of PKMYT1 significantly affected the mitotic index of glioblastoma and human neural progenitor cells." (PMID 40702552, 2025). "Loss of PKMYT1 dramatically influences the mitotic index of glioblastoma and human neural progenitors, and a similar phenotype is observed in HeLa cells knockdown of PKMYT1 by siRNA." (PMID 38570712, 2024). "As for the compound’s CNS permeability, while it could be exploited in the context of CNS malignancies like glioblastoma where PKMYT1 is also overexpressed, this property necessitates neurotoxicity evaluation during preclinical development." (PMID 40606600, 2025).
lung adenocarcinoma (6 papers, 2020 to 2024). A carcinoma that arises from the lung and is characterized by the presence of malignant glandular epithelial cells. "In lung adenocarcinoma, silencing PKMYT1 could prevent G2/M phase arrest and caused cells more sensitive to radiation." (PMID 36793346, 2022). "In another study, PKMYT1 was identified as a promising target to enhance the radio sensitivity of lung adenocarcinoma (LUAD)." (PMID 38291367, 2024). "Reports have shown that PKMYT1 activates the notch signaling pathway and enhances proliferation and tumorigenesis in lung adenocarcinoma." (PMID 35114989, 2022). "Our findings suggested that PKMYT1 is a promising target to improve the radiosensitivity of lung adenocarcinoma." (PMID 32411179, 2020).
lung cancer (5 papers, 2022 to 2025). A malignant neoplasm involving the lung. "In lung cancer, protein kinase membrane-associated tyrosine/threonine 1 (PKMYT1) might be related to the activation of the MAPK signaling pathway and 4EBP1 phosphorylation, promoting cell proliferation and apoptosis resistance." (PMID 39228892, 2024). "Pkmyt1, Plk1, and Ttk are upregulated in lung cancer and are considered oncogenes due to their function in promoting cell proliferation." (PMID 39273313, 2024). "In the TCGA databases, PKMYT1 expression was significantly higher in both LUAD and LUSC lung cancer tissues compared to normal lung tissues." (PMID 40702552, 2025).
pancreatic cancer (5 papers, 2021 to 2025). "PKMYT1 is a validated therapeutic target in pancreatic cancer due to its critical role in controlling the G2/M transition of the cell cycle." (PMID 40606600, 2025). "Collectively, these results support HIT101481851 as a potential lead compound for further development of PKMYT1-targeted therapies against pancreatic cancer." (PMID 40606600, 2025). "In conclusion, PKMYT1, markedly upregulated in pancreatic cancer, functions as an oncogenic promoter of tumorigenesis." (PMID 40664640, 2025). "PKMYT1 inhibitor (RP-6306), modulates the cell cycle progression and induces PANoptosis in pancreatic cancer cells, thereby inhibiting tumor growth and proliferation both in vitro and in vivo." (PMID 40664640, 2025). "As a targeted inhibitor of the serine/threonine kinase PKMYT1, we evaluated the effects of RP-6306 on pancreatic cancer cell lines." (PMID 40664640, 2025). "PKMYT1 is a well-established therapeutic target in pancreatic cancer due to its critical role in regulating cell cycle progression and tumor proliferation." (PMID 40606600, 2025). "In this study, we employed a combination of computer-aided drug design (CADD) and experimental validation to screen and identify novel PKMYT1 inhibitors with potential application in pancreatic cancer therapy." (PMID 40606600, 2025). "The interaction between CKS1B and PKMYT1 can disrupt the G2/M checkpoint, dysregulate the cell cycle, and promote abnormal proliferation in pancreatic cancer." (PMID 40857024, 2025). "Notably, PKMYT1 exhibited the most significant expression disparity between tumor and adjacent normal tissues in pancreatic cancer, and survival analyses have substantiated a significant correlation between PKMYT1 expression and the prognosis of pancreatic cancer, underscored by its P-value." (PMID 40664640, 2025). "Interestingly, PKMYT1 dropout sensitized pancreatic cancer cells to gemcitabine (Fig. EV2J)." (PMID 38570712, 2024). "Analysis by online website UALCAN revealed a positive correlation between PKMYT1 and PLK1 expression in pancreatic cancer cohorts (Fig. EV4F)." (PMID 38570712, 2024).
prostate carcinoma (5 papers, 2020 to 2025). A carcinoma that arises from epithelial cells of the prostate gland. "A kinome-wide CRISPR-Cas9 knockout screen reveals that FZD6 inhibition sensitizes prostate cancer cells to the inhibition of PKMYT1, a WEE kinase family member." (PMID 41286306, 2025). "According to our study, the high expression of PKMYT1 and RRM2 was correlated with prostate cancer oncogenesis and poor prognosis, indicating their potential oncogenic roles in prostate cancer." (PMID 32180804, 2020). "PKMYT1 promoted the growth of cells by targeting CCNB1 and CCNE1 in prostate cancer." (PMID 36793346, 2022). "Currently the functional significance of PKMYT1 in prostate cancer remains unclear, and it makes sense to determine whether PKYMT1 is indispensable in prostate cancer, which requires further investigation." (PMID 32180804, 2020).
neuroblastoma (4 papers, 2015 to 2024). Neuroblastoma (NB) is the most common solid, extracranial childhood tumor. "Depletion of PKMYT1 caused a drastic reduction of MYCN protein in most of the neuroblastoma cell lines analyzed." (PMID 25477524, 2015). "Cocktails of small molecule inhibitors of CKS1B, AHCY, BLM, and PKMYT1 profoundly affected the growth of all neuroblastoma cell lines but selectively caused death of MYCN-amplified cells." (PMID 25477524, 2015). "We showed here that PKMYT1 is required to stabilize the MYCN protein in neuroblastoma cells by reducing T58 phosphorylation by the cdk1/gsk3 kinases, explaining the synthetic lethal effect of PKMYT1 inactivation in MYCN-amplified cells." (PMID 25477524, 2015). "The significance of BLM, AHCY, PKMYT1, and CKS1B in the pathogenesis of neuroblastoma is indicated by their elevated expression in MYCN-amplified tumor samples and in MYCN-overexpressing cells and their correlation with poor patient survival." (PMID 25477524, 2015). "PKMYT1 inhibition was effective in MYCN-amplified neuroblastomas, but not neuroblastomas without amplification." (PMID 38279263, 2024).
glioma (3 papers, 2022 to 2023). A benign or malignant brain and spinal cord tumor that arises from glial cells (astrocytes, oligodendrocytes, ependymal cells). "We noted that combined WEE1 and PKMYT1 genetic ablation was lethal in a glioma setting." (PMID 37325550, 2023).
osteosarcoma (3 papers, 2020 to 2025). A usually aggressive malignant bone-forming mesenchymal neoplasm, predominantly affecting adolescents and young adults. "Moreover, apoptosis induced by cisplatin, the most widely used chemotherapy drug for osteosarcoma, was dramatically elevated in these knockout cells, although stable knockout of PKMYT1 alone also induced apoptosis in 143B cells." (PMID 32944406, 2020). "We further validated that TRRAP, PKMYT1, and TP53RK are required for osteosarcoma cell proliferation and colony formation." (PMID 32944406, 2020). "Among these targets, we analyzed 3 kinases, TRRAP, PKMYT1, and TP53RK, to validate their oncogenic functions in osteosarcoma." (PMID 32944406, 2020). "Consequently, we decided to validate whether the 3 other hits from our screening, TRRAP, PKMYT1, and TP53RK, were truly essential in osteosarcoma cell lines, given that their functions in osteosarcoma remain unknown." (PMID 32944406, 2020).
renal clear cell carcinoma (3 papers, 2021 to 2023). "Association between PKMYT1 mRNA expression and clinical characteristics of patients with clear cell renal cell carcinoma." (PMID 34959223, 2021). "In renal clear cell carcinoma, PKMYT1 was up-regulated and PKMYT1 was positively correlated with the anti-silencing effects of ASF1B gene." (PMID 36947060, 2023). "In renal clear cell carcinoma, radiation-induced G2/M phase arrest was eliminated when PKMYT1 was knocked down." (PMID 36793346, 2022).
breast tumors (2 papers, 2023 to 2024). "We obtained 5 prognosis-related genes, as the key biomarkers by Lasso-cox analysis (FBXL19, HAGHL, PHKG2, PKMYT1, and TXNDC17), all of which were significantly upregulated in breast tumors." (PMID 36747547, 2023). "Paired t-tests comparing the gene expression profiles of CACNG4, PKMYT1, EPYC, and CHRNA6 between breast tumors and normal tissues revealed an almost 5.55-fold, 2.31-fold, 2.32-fold, and 2.14-fold increase in breast tumors, compared to normal tissues, respectively." (PMID 38291367, 2024).
kidney cancer (2 papers, 2020 to 2021). Primary or metastatic malignant neoplasm involving the kidney. "Other computational studies have also identified PKMYT1 as a prognostic marker in kidney cancer cohorts." (PMID 33801837, 2021). "Other computational work has identified PKMYT1 as a novel drug target for kidney cancer, using co-expression analysis to reveal PKMYT1 clusters with other important cell-cycle genes." (PMID 33205077, 2020).
triple-negative breast carcinoma (2 papers, 2022 to 2023). An invasive breast carcinoma which is negative for expression of estrogen receptor (ER), progesterone receptor (PR), and human epidermal growth factor receptor 2 (HER2). "The analysis of single-cell sequencing indicated that PKMYT1 expression was upregulated in triple-negative breast cancer (TNBC), consistent with the results of bulk RNA-sequencing." (PMID 36793346, 2022).
acute lymphoblastic leukemia (1 paper, 2020). Leukemia with an acute onset, characterized by the presence of lymphoblasts in the bone marrow and the peripheral blood. "Our group showed that WEE1 kinase is highly expressed in acute lymphoblastic leukemia (ALL) cell lines and primary cells in comparison with normal hematopoietic cells, and that PKMYT1 is upregulated in relapsed ALL samples compared with nonmalignant hematopoietic cells." (PMID 32958072, 2020).
amyotrophic lateral sclerosis (1 paper, 2022). Amyotrophic lateral sclerosis (ALS) is a neurodegenerative disease characterized by progressive muscular paralysis reflecting degeneration of motor neurons in the primary motor cortex, corticospinal tracts, brainstem and spinal cord.
esophageal cancer (1 paper, 2021). A primary or metastatic malignant neoplasm involving the esophagus. "MELK and PKMYT1 (a dark kinase gene) have been identified as promising therapeutic targets in multiple cancers, such as the brain, colorectal, breast, ovarian, and esophageal cancers, respectively." (PMID 33801837, 2021).
leukemia (1 paper, 2025). A malignant (clonal) hematologic disorder, involving hematopoietic stem cells and characterized by the presence of primitive or atypical myeloid or lymphoid cells in the bone marrow and the blood. "PKMYT1 knockdown significantly suppressed K562 cell growth and proliferation, suggesting its involvement in leukemia progression." (PMID 40279509, 2025). "In an orthotopic xenograft model, PKMYT1 knockdown delays leukemia progression and reduces lymph node metastasis, reinforcing its role in CML progression and metastasis." (PMID 40279509, 2025). "To reveal the role of PKMYT1 in leukemia, we identified PKMYT1 as an oncogenic factor that promotes CML progression using data sets from multiple web‐based sources." (PMID 40279509, 2025). "Knocking down PKMYT1 significantly slowed tumor growth in both ectopic and orthotopic xenograft models and prolonged the survival period in a leukemia mouse model." (PMID 40279509, 2025). "All the mice inoculated with wild‐type K562 cells died within two weeks after disease onset, whereas those injected with PKMYT1‐knockdown K562 cells presented delayed leukemia onset and slower leukemia progression, with a survival time of up to 40 days from onset." (PMID 40279509, 2025).
liver cancer (1 paper, 2024). An epithelial or non-epithelial malignant neoplasm that arises from the liver. "The identification of safe and potent dual-targeting PKMYT1/HDAC2 inhibitors by molecular docking-based virtual screening is a particularly important strategy for the treatment of liver cancer." (PMID 39619613, 2024). "Herein, we report a discovery of novel and highly potent dual-targeting PKMYT1/HDAC2 inhibitors through virtual screening and subsequent biological evaluation for the treatment of liver cancer." (PMID 39619613, 2024). "However, to our knowledge, there have been no reports to date of dual-targeting inhibitors for PKMYT1, a member of the WEE kinase family, and HDAC2 for the treatment of liver cancer." (PMID 39619613, 2024).
lymph node metastasis (1 paper, 2025). "The expression of PKMYT1 was not statistically significant concerning patient age, and lymph node metastasis (p > 0.05); however, differences in histological grade, LAG-3, CD244, estrogen receptors, progesterone receptors, and Her-2 expression were statistically significant (p < 0.05)." (PMID 40821907, 2025).
Lymphatic Metastasis (1 paper, 2021). Transfer of a neoplasm from its primary site to lymph nodes or to distant parts of the body by way of the lymphatic system. "The results showed that high proportions of higher T stage, distant metastasis, advanced stage, lymphatic metastasis, and higher grade in the high expression group of PKMYT1." (PMID 34959223, 2021).
melanoma (1 paper, 2020). A malignant, usually aggressive tumor composed of atypical, neoplastic melanocytes. "We additionally confirmed the expression with mRNA levels of key genes after treatment with lj-1-59 in melanoma cells, which indicated that P21, BBC3, SESN2 and GADD45A expression were significantly upregulated, while MCM2, MCM3, MCM4, MCM7 and PKMYT1 were significantly downregulated." (PMID 32021565, 2020).
pancreatic adenocarcinoma (1 paper, 2021). "Here, we employed WGCNA to identify novel hub genes including PKMYT1, WDHD1, ASF1B, and RAD18, and proposed for the first time their oncogenic roles during pancreatic adenocarcinoma progression." (PMID 35047023, 2021).
prostate adenocarcinoma (1 paper, 2022). "The abnormal expression of PKMYT1 has been associated with soft tissue sarcoma, prostate adenocarcinoma, and squamous cell carcinoma of the cervix, among other neoplasms, although its role in tumorigenesis still has not been thoroughly investigated." (PMID 35884597, 2022).
thyroid cancer (1 paper, 2023). "Although no data are available on the role of this gene in thyroid cancer, PKMYT1 has been shown to exert an important effect on tumor immunity and progression in several cancer models." (PMID 37208504, 2023).